MTOR (mechanistic target of rapamycin kinase)
Diseases named in the same sentence as MTOR in open-access papers (continued):
Sharing a sentence is not in itself a finding about the gene and the disease.
cataract (5 papers, 2022 to 2025). Partial or complete opacity of the crystalline lens of one or both eyes that decreases visual acuity and eventually results in blindness. "Therefore, further research on the association between mTOR-dependent protein level and subtype of cataracts is required." (PMID 36271348, 2022). "Additionally, fasting alcohol intake increases hyperhomocysteinemia risk fivefold, which may exacerbate cataracts via mTOR activation, impaired autophagy, and reduced connexin expression." (PMID 41416118, 2025).
childhood cancers (5 papers, 2016 to 2024). "Potent and selective inhibitors of PI3K and/or mTOR pathways have entered clinical trials in both adult and pediatric cancers, and could be valuable agents for treatment of childhood cancers." (PMID 27438153, 2016).
chronic GVHD (5 papers, 2014 to 2022). "Chronic GvHD: The importance of mTOR signaling for GvHD pathogenesis is underlined by the finding of activating mTOR mutations in cGvHD patients which drive clonal CD4+ T-cell expansion and cGvHD development." (PMID 34868001, 2021). "Here we report studies of a patient with chronic GvHD (cGvHD) carrying persistent CD4+ T cell clonal expansion harboring somatic mTOR, NFKB2, and TLR2 mutations." (PMID 32382059, 2020). "Examples include the mTOR inhibitor sirolimus for acute or chronic GVHD, or dasatinib for chronic GVHD, both which has been shown in vitro to directly inhibit growth of some cases of JMML." (PMID 24734223, 2014).
chronic lung disease (5 papers, 2013 to 2023). According to the definitions of the American and British Thoracic Societies, including pulmonary functional tests, X-rays, and CT scans for items such as fibrosis, bronchiectasis, bullae, emphysema, nodular or lymphomatous abnormalities. "Reactivation and dysregulation of the developmental signaling pathway mTOR are a hallmark of aging and chronic lung diseases." (PMID 37874650, 2023). "Patients receiving mTOR inhibitors should be carefully monitored for the evidence of infection, especially patients with underlying known chronic lung disease or risk factors of infection." (PMID 23785409, 2013). "Reactivation and dysregulation of the mTOR signaling pathway are a hallmark of aging and chronic lung disease; however, the impact on microvascular progenitor cells (MVPCs), capillary angiostasis, and tissue homeostasis is unknown." (PMID 37874650, 2023).
ciliopathies (5 papers, 2016 to 2025). "Furthermore, the ORAs also matched several signaling pathways, including WNT-, Hippo-, Hedgehog, and mTOR signaling which have not only been linked to ciliogenesis and/or ciliopathies before, but also directly to PALS1." (PMID 39614182, 2024). "Next to cAMP signaling, an important signaling pathway that is inappropriately activated in ciliopathies is the mammalian target of rapamycin (mTOR) which functions as a central regulator in cellular metabolism, growth, proliferation, cell cycle and survival." (PMID 34055783, 2021). "Since ciliopathies often increase mTOR activity, the presence of intact cilia seems to shift the balance towards autophagy, keeping mTOR activity under control." (PMID 28361305, 2017). "Importantly, our results require further research to understand the pathways connecting the primary cilium, mTOR signaling and cystogenesis in ciliopathies." (PMID 28529994, 2016). "In ciliopathies like PKD, flow sensing is altered leading to mTOR pathway activation and uncontrolled cell growth and proliferation which induces cystogenesis." (PMID 34055783, 2021).
colorectal adenoma (5 papers, 2015 to 2022). An adenoma that arises from the colon or rectum. "Some scholars have found significantly enriched eIF6 expression and PI3K/AKT/mTOR signals in colorectal adenomas." (PMID 34922580, 2021). "The results showed that in colorectal adenomas and high-grade intraepithelial neoplasia CRC glandular elements, components of mTOR signaling, including mTOR, p70s6 K and 4EBP1, were strongly activated." (PMID 36428613, 2022).
cystic fibrosis (5 papers, 2017 to 2025). Autosomal recessive disorder caused by pathogenic variants in the CFTR gene (cystic fibrosis transmembrane conductance regulator), which encodes a chloride and bicarbonate channel expressed in epithelial cells, and follow the diagnosis criteria. "Although both patient groups had equal exposure to immunosuppressant drugs (defined as corticosteroids, calcineurin inhibitors, mTOR inhibitors, thiopurines and biologics), only patients (n=2) in the cystic fibrosis cohort had previous solid organ transplants." (PMID 28765714, 2017). "Previous studies have demonstrated that mTOR inhibitors reduce inflammation in cystic fibrosis 80–82, while reduced ubiquitin-mediated proteolysis has been linked to decreased inflammation and increased CFTR cell surface expression." (PMID 40501816, 2025).
diffuse intrinsic pontine glioma (5 papers, 2016 to 2024). A neuroglial tumor that arises from the middle portion of the brain stem. "This is consistent with observations that ridaforolimus crosses the blood–brain barrier and that the benefit of single-agent therapy with an mTOR inhibitor is characteristically disease stabilization, including in patients with diffuse intrinsic pontine glioma." (PMID 27713169, 2016).
dyslipidaemia (5 papers, 2015 to 2024). "Dyslipidaemia is a well-known dose-dependent adverse effect of mTOR inhibitors that is thought to occur through down-regulation of low-density lipoprotein receptors and inhibition of lipoprotein lipase activity." (PMID 26020944, 2015). "Additionally, dyslipidaemia post-transplantation is exacerbated by mammalian target of rapamycin (mTOR) inhibitors." (PMID 35268313, 2022). "We also found a potential causal link between blood levels of BCAAs and lipid profiles, proposing that BCAAs, such as leucine, could activate the mTOR signalling pathway in a manner distinct from insulin, suggesting that BCAAs may directly affect lipid metabolism and contribute to dyslipidaemia." (PMID 38711861, 2024).
Epstein-Barr virus infection (5 papers, 2018 to 2024). An infection that is caused by Epstein-Barr virus. "In Epstein-Barr virus infection, niclosamide suppresses viral lytic replication by inhibiting mTOR (mammalian target of rapamycin) activation." (PMID 30125275, 2018).
focal segmental glomerulosclerosis (5 papers, 2020 to 2026). A renal disorder characterized by sclerotic lesions in the glomeruli. "At 18 months, sirolimus was switched to mycophenolate mofetil because of proteinuria and focal and segmental glomerulosclerosis associated with mTOR inhibitors." (PMID 35864198, 2022). "In BHDS patients, maintenance therapy with mTOR inhibitors might be considered after the initial wound-healing period but should be done so with caution due to the risk of podocyte apoptosis and potential development of focal segmental glomerulosclerosis." (PMID 40740168, 2025). "Furthermore, constitutive mTOR activation is capable of inducing glomerular lesions in mice, whilst its partial blockade may ameliorate focal segmental glomerulosclerosis (FSGS)-like conditions." (PMID 35290515, 2022).
frontotemporal dementia (5 papers, 2017 to 2026). Frontotemporal dementia (FTD) comprises a group of neurodegenerative disorders, characterized by progressive changes in behavior, executive dysfunction and language impairment, as a result of degeneration of the medial prefrontal and frontoinsular cortices. "The mTOR signalling cascade (mTORC1/2) is implicated in neurodegenerative mechanisms across multiple disorders, including frontotemporal dementia (FTD) and PD, where it modulates autophagy, protein aggregation, and synaptic plasticity." (PMID 41477452, 2025). "Meanwhile, the phosphoinositide 3-kinase (PI3K)-Akt-mammalian target of rapamycin (mTOR) pathway regulates the imbalance between autophagy and apoptosis, and this balancing act also impacts PD, HD, frontotemporal dementia (FTD), and ALS." (PMID 39337436, 2024). "The framework also incorporates opposing phosphoinositide 3-kinase (PI3K)/AKT/mechanistic target of rapamycin (mTOR) and peroxisome proliferator-activated receptor-gamma coactivator-1alpha (PGC-1α) pathway patterns that may distinguish ALS from frontotemporal dementia (FTD) within an aging context." (PMID 42164014, 2026).
germinoma (5 papers, 2016 to 2025). A malignant germ cell tumor arising in the central nervous system. "Upregulation of PI3K pathway is the second genetic event involved in germinoma pathogenesis, MTOR gene being frequently mutated." (PMID 34357128, 2021). "Recurrent somatic mutations in the KIT/RAS/MAPK pathways and AKT/mTOR pathways have been well documented in intracranial GCTs, with KIT/KRAS/MAPK alterations known to be enriched in germinomas." (PMID 39959669, 2025). "Unlike the more frequent alterations observed in the KIT/RAS pathway in germinomas, the occurrence rate of mutations in the AKT/mTOR pathway was similar between germinomas and NGGCTs." (PMID 38790424, 2024). "Recurrent mutations have been detected in the MAPK or PI3K pathways, most typically in KIT and MTOR and low genome-wide methylation has been demonstrated in germinoma; this most likely reflects the cell-of-origin primordial germ cells for this tumor type." (PMID 36132131, 2022). "The main mTOR targets in germinomas and their functional roles have to be identified in future studies." (PMID 27391150, 2016). "Furthermore, we discovered activation of the Akt/mTOR pathway by immunohistochemistry in 94.4% and upregulation of ERK pathway in 88.5% of germinomas." (PMID 27391150, 2016). "Interestingly, pS6 was found to be negative in 57.4% of cases indiacting that this component is not the preferentially phosphorylated target of mTOR in germinomas." (PMID 27391150, 2016).
Hutchinson-Gilford progeria syndrome (5 papers, 2013 to 2025). "Apart from this link to genomic instability and senescence, it has been found in a mouse model of Hutchinson-Gilford progeria that AMPK activation and mTOR inhibition occurs in conjunction with activation of autophagy." (PMID 27213333, 2016). "There is currently no effective treatment for Hutchinson-Gilford progeria syndrome, and these data provide hope that rapamycin derivatives or other mTOR inhibitors might slow disease progression in Hutchinson-Gilford progeria syndrome patients." (PMID 24379984, 2013).
hypopharyngeal carcinoma (5 papers, 2012 to 2023). Carcinoma, predominantly squamous cell, arising from the epithelial cells of the hypopharynx. "Our data revealed that the mTOR expression levels were significantly upregulated in hypopharyngeal cancer (p = 0.030)." (PMID 29760955, 2018). "In addition, metformin induced p27(Thr198) phosphorylation through activation of MEK/ERK/RSK and AMPK/mTOR signaling pathways, and consequently directed hypopharyngeal cancer cells toward autophagy." (PMID 33652909, 2021). "The activation status of the PI3K/AKT/mTOR pathway was investigated in our series of 93 laryngeal and hypopharyngeal carcinomas by analyzing the immunohistochemical expression of multiple upstream and downstream components, such as EGFR, PDK1, PTEN, p-AKT and p-S6." (PMID 27119232, 2016). "Therefore, targeting of PI3K-Akt-mTOR signaling could be a reasonable strategy in the treatment of hypopharyngeal cancer where systemic therapy is effective, especially in advanced disease." (PMID 29760955, 2018). "NR120519 activated the AKT/mTOR pathway and EMT by blocking KRT17 and promoted cell proliferation and migration of hypopharyngeal carcinoma in vitro and cell proliferation in vivo." (PMID 36765563, 2023). "RIP and WB assays showed that KRT17 was associated with and blocked by NR120519.The silencing of KRT17 promoted cell proliferation and the migration of hypopharyngeal carcinoma in vitro and cell proliferation in vivo by activating the AKT/mTOR pathway and epithelial-mesenchymal transformation (EMT)." (PMID 36765563, 2023).
hypoxic-ischemic encephalopathy (5 papers, 2017 to 2024). "An elegant experimental study observed that BDNF activates autophagy by inhibiting the mTOR pathway in rats with hypoxic-ischemic encephalopathy." (PMID 38006577, 2024). "The authors examined the role of fragile X mental retardation protein (FMRP) and mammalian target of rapamycin (mTOR) signaling pathway in the pathogenesis of hypoxic-ischemic encephalopathy." (PMID 28331572, 2017). "In a neonatal hypoxic-ischemic encephalopathy model, intraperitoneal injection of MT (15 mg/kg) into pups 1 h before hypoxia induction upregulated the expression of NLRX1, which downregulated mTOR expression and promoted ATG7 and Beclin-1 expression to promote mitophagy and inhibit apoptosis." (PMID 38786094, 2024).
Impaired glucose tolerance (5 papers, 2021 to 2025). An abnormal resistance to glucose, i.e., a reduction in the ability to maintain glucose levels in the blood stream within normal limits following oral or intravenous administration of glucose. "These mice displayed impaired glucose tolerance and reduced GLP-1 production through the CaMKKII-CaMKIV-mechanistic target of rapamycin (mTOR) pathway." (PMID 40446026, 2025). "Moreover, miR-let-7-mediated repression of multiple components of the insulin-PI3K-mammalian target of rapamycin (mTOR) pathway, including INSR and IRS2, leads to impaired glucose tolerance." (PMID 34298896, 2021).
intraepithelial neoplasia (5 papers, 2015 to 2025). A precancerous neoplastic process that affects the squamous, glandular, or transitional cell epithelium without evidence of invasion. "KRAS mutations lead to constitutive activation of the RAS protein, resulting in activation of the RAF/MEK/ERK pathway or PI3K/PDK1/AKT/mTOR pathway and, ultimately, the development of intraepithelial neoplasia." (PMID 39941707, 2025). "Proteogenomics reveals LYN amplification at the chromosome 8q gain functioned in the transmit from intraepithelial neoplasia phase to infiltration tumor phase via MAPK signaling, and illustrates the DST mutation improves mTOR signaling in the duodenal adenocarcinoma stage." (PMID 36991000, 2023).
latent infection (5 papers, 2022 to 2024). "Additionally, mTOR inhibitors can modulate the immune response in a context-dependent manner, potentially increasing susceptibility to opportunistic infections or reactivation of latent infections." (PMID 39682184, 2024). "The exact pathophysiology of EBV-SMT is not clear though it is believed to involve the reactivation of latent infection through mTOR pathways." (PMID 39726470, 2024). "Epigenetics of the provirus fueled by metabolism and mTOR signaling likewise controls active and latent infection." (PMID 36467738, 2022).
leishmaniasis (5 papers, 2018 to 2025). Infectious disease that is transmitted through the bite of hematophagous female phlebotomine sand flies. "Taken together, our findings suggest that select mTOR inhibitors may be used in therapeutic settings for the management of leishmaniasis." (PMID 30133440, 2018). "The mTOR pathway tightly regulates 4E-BP1, but in leishmaniasis, GP63-induced cleavage of mTOR blocks mTORC1 activation and inhibits 4E-BP1 phosphorylation." (PMID 40920481, 2025). "Our results demonstrate, for the first time to our knowledge, that inhibition of mTOR by rapamycin or GSK-2126458 decreases the parasite burden dramatically and reduce the morbidity of experimental leishmaniasis impressively." (PMID 30133440, 2018). "Future studies will also need to test the effect of rapalogs and dual mTOR/PI3K inhibitors in the context of infection with other strains of Leishmania and in other forms of leishmaniasis." (PMID 30133440, 2018). "Thus far, Fyn has not been reported to have a direct link to leishmaniasis, but it has been shown that inhibiting Fyn/Lck kinase activity prevents Treg differentiation into Th17 cells through the AKT/mTOR pathway." (PMID 39696675, 2024).
lung carcinoid (5 papers, 2018 to 2025). "An effect of cabergoline in potentiating the effect of everolimus administration by a reduction of the mTOR inhibitor-induced escape mechanisms was previously reported in lung carcinoid tumoral cells." (PMID 35721701, 2022). "The diagnosis of lung carcinoid tumors requires data on neuroendocrine differentiation, which is recognized by positive immunohistochemical (IHC) stains for Ki-67, mTOR, and chromogranin A." (PMID 33557782, 2021). "In H727 and UMC11 lung carcinoid cells, miR-100 modulated mTOR RNA and TORC1 complex protein expression, positively promoted cell migration and negatively influenced cell proliferation." (PMID 29938004, 2018). "Our aim was to analyze the expression and functional role of specific miRNAs in lung carcinoids as an alternative mechanism targeting mTOR pathway." (PMID 29938004, 2018). "Mammalian target of rapamycin (mTOR) is a promising therapeutic target in advanced lung carcinoid patients." (PMID 29938004, 2018). "The link between the NRF2 system of sensing environmental stress and mTOR may suggest a possible role of KEAP1/NRF2 deregulation observed in lung carcinoids in prediction to response to mTOR pharmacological inhibition in these tumors." (PMID 31126053, 2019). "First, we validated which of the three miRNAs showing the best inverse correlation with mTOR at the tissue level (miR-100, miR-193a-3p and miR-193a-5p) directly represses mTOR expression in lung carcinoid cells, a preliminary step for further functional studies." (PMID 29938004, 2018). "They showed that regulation of mTOR mRNA and TORC1 protein levels by miR‐100 leads to enhanced cell migration and reduced cell proliferation in H727 and UMC11 lung carcinoid cell lines." (PMID 40754657, 2025). "Several microRNAs (miRNAs) have been reported to selectively modulate mTOR pathway in other tumor models, but never in lung carcinoids." (PMID 29938004, 2018). "Indeed, while high levels of mTOR activation have been described in lung carcinoids in “prevalence” studies, no data are available about the correlation between specific activation profiles and response to therapy." (PMID 29938004, 2018). "The lack of wide correlation data between mTOR expression and mTOR inhibitor responsiveness make our results speculative, and our case series failed to be supportive of this hypothesis since no lung carcinoid patient in our cohort was treated with mTOR inhibitors at the time of this study." (PMID 29938004, 2018).
Lymphadenopathy (5 papers, 2017 to 2024). Enlargement (swelling) of a lymph node. "We initially hypothesized that hyperactive mTOR signaling may drive the abnormal proliferation of DNTs, based on our work in preclinical ALPS models demonstrating that the mTOR inhibitor sirolimus was effective in reducing DNTs, lymphadenopathy, splenomegaly, and autoantibodies in thelpr mice." (PMID 29123652, 2017). "Notably, Sirolimus treatment has also ameliorated lymphadenopathy and hepatosplenomegaly, and NK cell function in some APDS/PASLI patients, implicating mTOR in these phenotypes." (PMID 30116245, 2018).